CD36 (CD36 molecule (CD36 blood group))
Diseases named in the same sentence as CD36 in open-access papers (continued):
Sharing a sentence is not in itself a finding about the gene and the disease.
tumor (continued). "Inhibition of CD36-mediated lipid metabolism and signaling pathways may reduce tumor growth and metastatic potential." (PMID 42164471, 2026). "Increased CD36 expression promotes enhanced fatty acid uptake, which supports tumor cell proliferation, migration and survival, by mediating metabolic reprogramming and interacting with the tumor microenvironment." (PMID 42164471, 2026). "The downregulation of CD36, collagen I, and 4E-BP1 is associated with tumor suppression." (PMID 40733687, 2025). "In addition, CD36 can also induce tumor immune tolerance and progression by driving lipid metabolic reprogramming in tumor-associated immune cells." (PMID 39984452, 2025). "Future studies should delineate how CD36 interfaces with subtype‐defining pathways and explore whether its tumor‐suppressive effects in TNBC involve mechanisms beyond lipid metabolism, such as immune modulation or anoikis resistance." (PMID 41267927, 2025). "Studies assessing fatty acid synthase, enoyl-CoA hydratase short-chain 1 (ECHS1), HDL-Receptor SR-BI, the lipid transporter CD36, FA catabolic enzymes or the fatty acid transport protein 4 suggest that these genes regulate ccRCC tumor growth and can predict patient survival." (PMID 40902455, 2025). "To test whether interference with CD36 blocks tumor cell proliferation in PyMT-RIDad mice, we isolated tumor cells from PyMT and PyMT-RIDad mice and cultured them in vitro." (PMID 40526430, 2025). "This suggests that CD36 may drive cholesterol metabolic reprogramming in DLBCL by regulating de novo cholesterol synthesis in tumor cells, altering their metabolic patterns and acting as a critical driver of cholesterol metabolism in DLBCL." (PMID 41041664, 2025). "Similarly, Pfeiler et al92 showed that liver macrophage CD36 crucially promoted the engulfment of tumor microvesicles and controlled the extravasation of tumor microvesicles as well as premetastatic foci formation during liver metastasis of pancreatic cancer." (PMID 39774047, 2025). "In TAMs and Tregs, CD36 promotes an immunosuppressive environment, supporting tumor growth." (PMID 40370434, 2025). "LA may generate pro-inflammatory lipids (e.g., PGE2) via ω-6 PUFA pathways, while palmitic acid supports tumor growth through CD36-mediated lipid uptake." (PMID 40896442, 2025). "Furthermore, in a coculture system of RM-1/CXCR2 tumour cells with spleen-derived macrophages, CD36 inhibition markedly reduced M2 polarization." (PMID 41163221, 2025). "Research has revealed that CD36-mediated fatty acid uptake by tumor-infiltrating CD8+ T cells is capable of inducing lipid peroxidation and ferroptosis, subsequently leading to diminished cytotoxic production and ultimately attenuating their anti-tumor efficacy." (PMID 40260246, 2025). "Specifically, targeting the pathways involved in the upregulation of CD18 and CD36 might inhibit the pro-tumorigenic functions of neutrophils, thereby limiting tumor progression and metastasis." (PMID 40549016, 2025). "We identified CD36, MMP1, TGFBR3, TWIST2, ITGB1, and FGF19 as associated with poorer outcomes: CD36 enhances tumour stemness and growth, MMP1 facilitates metastasis, TGFBR3 and TWIST2 promote EMT and invasion, ITGB1 supports cell adhesion and survival, and FGF19 drives proliferation." (PMID 41007296, 2025). "Furthermore, evidence suggests that CD36 expression inhibits tumor aggressiveness, and high levels of CD36 expression correlate with extended patient survival and favorable prognoses." (PMID 40075313, 2025). "CD36 may serve as a potential target for tumor treatment, and combining CD36 inhibitors with anti-programmed death protein 1 (PD-1) has been shown to restore the anti-tumor immune response of T cells." (PMID 40248695, 2025). "Similarly, CD36-mediated uptake of oxidized low-density lipoproteins (OxLDL) in CD8+ tumor infiltrating lymphocytes (TILs) induced lipid peroxidation and promoted intratumoral CD8+ T cell dysfunction." (PMID 41550652, 2025).
tumor (continued). "A connection between CD36 expression and the tumor immune microenvironment is suggested." (PMID 40527069, 2025). "CD36 has been shown to facilitate evasion of therapy-induced metabolic stress in tumor cells." (PMID 40502769, 2025). "Additionally, scRNA‐seq analysis showed no significant upregulation of CD36 expression in macrophages within tumor samples, further diminishing the likelihood of CD36‐mediated uptake as the primary mechanism." (PMID 40552574, 2025). "Even within the same cancer type, CD36 can act as either an oncogene or a tumor suppressor." (PMID 41267927, 2025). "Tumor cells exhibit high expression of lipid transport proteins, including CD36, FABPs, and FATPs." (PMID 41345744, 2025). "Additionally, hypoxia-induced CD36 expression has been observed in peritoneal metastases, suggesting its role in fatty acid uptake and tumour spread." (PMID 41154605, 2025). "Interestingly, we found KPC tumor-induced increase in the gene expression of some of the molecules, especially Cd36, is significantly inhibited in Xbp1mKO mice compared with Xbp1fl/fl mice." (PMID 40655023, 2025). "We chose CD18 and CD36 due to their established roles in neutrophil biology and tumor immunity." (PMID 40549016, 2025). "In the subcutaneous xenograft mouse model, we observed that the tumor volume and weight in the PLIN2 overexpression group were greater than those in the control group, whereas the tumor volume and weight in the CD36 inhibitor group was smaller than that in the PLIN2 overexpression group." (PMID 40640171, 2025). "CD36, a key FA transporter, plays a complex role in tumor metabolism and immunity." (PMID 40370434, 2025). "Notably, TAMs exhibit high levels of CD36 expression, which facilitates their uptake of lipid-rich extracellular vesicles released by tumor cells." (PMID 40051496, 2025). "Levels of CD36 in neutrophils from TDLNs were similar to hLN and significantly lower than in tumor." (PMID 40549016, 2025). "In this regard, the pro-tumoral activity of G protein-coupled receptor 1 (GPR1) and CMKLR1 chemerin receptors has been recently demonstrated to induce FAAs uptake and the clear cell morphologic features in ccRCC, by modulation of tumor cells’ SREBP1c and CD36 expression." (PMID 40227577, 2025). "In some contexts, CAFs with low CD36 expression may produce more extracellular matrix components, which can support tumor growth and metastasis." (PMID 40051496, 2025). "CD36 supports HFD-driven tumor progression by preventing SFA-induced lipotoxicity." (PMID 40977744, 2025). "TAMs accumulate lipids (including oxidized species), adopt an OXPHOS/FAO-skewed program, and polarize toward wound-healing, immunosuppressive states through PPAR/LXR signaling; blocking fatty-acid uptake (e.g., CD36) or FAO can recondition TAMs toward inflammatory phenotypes across tumor models." (PMID 41394868, 2025). "TIPE2 and CD36 may be novel biomarkers for predicting tumor metastasis and prognosis in patients with bladder UC and hold promise as therapeutic targets." (PMID 40060230, 2025). "According to the cell fusion theory, preventing monocyte/cancer cell fusion with anti-PS or anti-CD36 antibodies could potentially impair the generation of new metastatic cancer cell clones and impede tumor progression and metastasis." (PMID 39752516, 2025). "This correlation suggests that CD36 might serve as a valuable prognostic indicator and could be explored as a target for therapeutic intervention, particularly in the modulation of tumor metabolism and immune response." (PMID 40061897, 2025). "Based on this foundation, a hydrogel-based delivery platform was engineered, which was designed to co-deliver tumor-targeting CuS NPs and the immune-suppressive cell-targeting CD36 inhibitor sulfo-N-succinimidyl oleate (SSO), ultimately forming iF-CuS-M/SSO@Gel." (PMID 41345744, 2025). "Here, we report a tumor‐suppressive function of CD36 in TNBC." (PMID 41267927, 2025).
tumor (continued). "Targeting CD36-mediated FA endocytosis not only serves as an invaluable method for preventing CCA recurrence but also as an effective strategy to increase the efficacy of tumor immunotherapy." (PMID 39984452, 2025). "The expression of CD36 in M-LDNs increased, especially in tumor tissues." (PMID 41214328, 2025). "Dysregulated CD36 activity impacts both tumor growth and immune cell function." (PMID 40370434, 2025). "Furthermore, CD36 reprograms the tumor-immune cell's functions resulting in tumor immune tolerance making CD36 a potential target for cancer therapy." (PMID 40060230, 2025). "Additionally, studies have shown that CD36 plays a significant role in tumor angiogenesis, epithelial–mesenchymal transition, and other processes." (PMID 41267927, 2025). "Taken together, these findings suggest that CD36 expression in neutrophils might require cellular interactions and signals that are unique to the in vivo tumor microenvironment." (PMID 40549016, 2025). "To explore whether the impaired protective role of pitavastatin in CD36−/− mouse is also related to lipid levels, we determined lipid profiles in serum and tumor tissues." (PMID 38319449, 2024). "The lipid transporter CD36 is highly expressed in tumor CD8+ T cells, impairing their function." (PMID 39402302, 2024). "In addition, H&E staining showed that tumor metastasis was suppressed in the lung tissues of CD36−/− mice." (PMID 38319449, 2024). "In this study, we investigated whether the selective inhibition of CD36 can inhibit tumor progression and facilitate an antitumor immune response in oral squamous carcinoma cells (OSCCs)." (PMID 39273384, 2024). "Moreover, enforced expression of glutamate-cysteine ligase catalytic subunit (Gclc) promotes glutathione synthesis and prevents CD36 upregulation, thus boosting T cell anti-tumor immunity." (PMID 38360744, 2024). "In addition, since VT1021 stimulates TSP-1 expression, which binds to CD36/CD47 on the surface of tumor cells, we also investigated the TSP-1 CNV in the NCI database." (PMID 39627379, 2024). "Compared to C57BL/6 J mice, tumor progression was largely impaired in CD36−/− mice." (PMID 38319449, 2024). "In conclusion, these findings demonstrate that Gclc facilitates glutathione synthesis and reduces glutamate-induced CD36 upregulation in cystine-starved T cells, thereby shielding T cells from exhaustion and ferroptosis, leading to enhanced anti-tumor immunity." (PMID 38360744, 2024). "Notably, the targeted suppression of CD36 expression rejuvenates the CD8 T cells’ anti‐tumour efficacy, thereby constraining tumour growth, highlighting a potential therapeutic avenue." (PMID 39083563, 2024). "Targeting CD36, using either drug-based treatments or genetic modification techniques, resulted in diminished stem-like traits in these cells and a notable slowing of tumor expansion." (PMID 39691192, 2024). "Further studies on CD36 revealed that its overexpression in intra-tumor effector T cells exposes them to oxidative damage and ferroptosis due to lipid accumulation, and combining anti-PD-1 therapy with CD36 or ferroptosis inhibitors offered greater immunotherapeutic benefits." (PMID 39119332, 2024). "More research targeting CD36 and interfering with FA uptake might be an effective strategy for tumor treatment." (PMID 38276607, 2024). "Its expression has been repeatedly presented as an unfavorable prognostic factor for various tumor types, raising the question: could CD36 be a critical factor in cancer treatment resistance?" (PMID 38370376, 2024). "Additionally, CD36 expression was found to be elevated in the plasma and tumor tissue of NSCLC patients." (PMID 38319449, 2024). "Mechanistically, CD36 is selectively upregulated in intratumoral Treg cells and enhances mitochondrial fitness via peroxisome proliferator-activated receptor-β (PPARβ) signaling, rewiring Tregs to adapt to a lactate-enriched tumor microenvironment." (PMID 38216787, 2024).
tumor (continued). "Although PtdSer is also present on the surface of apoptotic tumor cells and other efferocytosis receptors exist on DCs, such as the CD36-PtdSer pathway that mediates the recognition and uptake of apoptotic tumor cells, it is normally inhibited by the presence of the autophagy protein ATG5." (PMID 38835772, 2024). "Overall, our findings show that CB2R activation promotes TAMs-mediated phagocytosis of tumor cells by enhancing CD36 expression, implying that JWH133 could be a useful therapeutic approach to improving chemotherapeutic efficacy against GBM." (PMID 39691192, 2024). "However, arachidonic acid can also induce ferroptosis in tumor-infiltrating CD8+ T cells via CD36 expression." (PMID 39402302, 2024). "In addition, CD36 expression in the tumor tissues of NSCLC patients was much higher than that in adjacent tissues." (PMID 38319449, 2024). "Interestingly, in this study we found an association of increased FABP4 and CD36 mRNA expression with poor prognosis in CRC, further suggesting the tumor-promoting properties of lipid metabolism upregulation." (PMID 39147895, 2024). "The transfer of FAs from the adipocytes to the tumor cells is realized by CD36 and FABP4." (PMID 39085485, 2024). "Additionally, the expression of ANGTPL4 and CD36, proteins involved in fatty acid metabolism, was increased in the marginal tumor cells of these patients." (PMID 39456610, 2024). "In the context of macrophages, it was shown that CD36-mediated metabolic crosstalk between tumor cells and macrophages could promote liver metastasis." (PMID 38962317, 2024). "This shows that tumor-secreted factors play a role in upregulating CD36 in SLN prior to metastasis." (PMID 39062552, 2024). "CD36 within the TME has a distinct role in the vascular endothelium, tumor-associated macrophages, myeloid-derived suppressor cells (MDSCs), regulatory T (Treg) cells, and CD8+ T cells in tumor growth." (PMID 39062552, 2024). "It has been reported that tumor cells upregulate CD36 to resist different treatments." (PMID 39627379, 2024). "Moreover, CD36 silencing decreased intracellular lipid content and hindered the development of tumor cells mediated by miRNA-2176." (PMID 38370376, 2024). "More importantly, CD36 is a significant regulator of tumor growth, metastasis, and angiogenesis." (PMID 39062552, 2024). "CD36 is involved in tumor pathogenesis by regulating the mitochondrial gene PPAR." (PMID 39103344, 2024). "In addition, the involvement of CD36 in various disease processes, including cholesterol efflux, tumor growth and adhesion, and platelet activation, through the regulation of downstream MAPK cascades has been documented." (PMID 39107881, 2024). "Acetate and CD36 were significantly elevated in peripheral tumours of LumB in our results." (PMID 38332687, 2024). "According to this study, tumor angiogenesis may be driven by the downregulation of CD36 in the tumor endothelium." (PMID 38370376, 2024). "Recently, CD36 has been concluded by increasing studies that it contributes to promoted tumor formation, growth, metastasis, enhanced chemoresistance and radio-resistance, disrupted anti-tumor Immune responses, etc.." (PMID 38765144, 2024). "If upregulation of CD36 levels on tumor cells is a prerequisite for malignant progression, this event on immune cells could dramatically impair the antitumor immune response." (PMID 39624081, 2024). "Taken together, these findings suggest that targeting CD36 may be a strategy to prevent tumor spread and metastasis." (PMID 39624081, 2024). "Moreover, cancer stem cell of glioblastoma can selectively use CD36 to maintain their renewal and capacity for tumor initiation." (PMID 38319449, 2024). "Finally, CD36, a multifunctional cell surface receptor that imports fatty acids, contributes to various aspects of PCa biology, including tumour growth, angiogenesis, and metastasis." (PMID 38969865, 2024).
tumor (continued). "The authors concluded a decrease in CD36 methylation after administering Decitabine, a DNA methylation inhibitor, and Chidamide, a particular class I histone deacetylase inhibitor, alone and in combination, ultimately inhibited tumor growth." (PMID 38370376, 2024). "Uptake of exogenous FAs into tumor cells primarily occurs through the process of fatty acid endocytosis, mediated by specialized transporters, including the fatty acid translocase/CD36, fatty acid transport protein family, and the plasma membrane fatty acid-binding proteins." (PMID 38500157, 2024). "While the IRS for FABP4 was comparable between the normal and overweight/obese group (8.80 versus 9.07), the IRS for ANGTPL4 (6.00 versus 9.80; p = 0.026) and CD36 (2.15 versus 2.60; p = 0.041) were both significantly higher in marginal tumor cells in the overweight/obese group." (PMID 39456610, 2024). "Attacking CD36 is a promising option for cutting off the FA uptake of tumor cells." (PMID 39085485, 2024). "We selected two additional tumor models, T11‐UV and T11‐Apobec, that displayed a high expression of Tgfb1 (both tumor models) and Tgfb2 (T11‐UV), high expression of Vimentin (Vim) and fibrotic marker (Pik3ca), and low expression of Cd36 and apoptosis regulator Bcl2." (PMID 39553439, 2024). "Extracellular vesicles (EVs) secreted by malignant melanocytes play a vital role in developing tumor-promoting microenvironments, but it is unclear whether this is mediated through CD36." (PMID 39062552, 2024). "Overall, our study elucidates that CB2R activation can promote TAMs-mediated phagocytosis of tumor cells by increasing CD36 expression, suggesting JWH133 could serve as a viable therapeutic approach to enhance the efficacy of chemotherapy in treating GBM." (PMID 39691192, 2024). "Tumor-derived-EV-exposed monocytes accumulate lipids as lipid droplets through upregulating CD36." (PMID 39062552, 2024). "However, we did not detect any significant changes in CD36 abundance in mice injected with HCT116 (MIIP+/− or WT) alone, suggesting that CD36 upregulation in tumor cells was attributed to adjacent adipose browning." (PMID 38245780, 2024). "Recently, the relationship between CD36 and tumor progression and metastasis has been a concern." (PMID 38276607, 2024). "Thus, inhibiting CD36 in intra-tumor Tregs through genetic ablation or using CD36 monoclonal antibodies effectively delayed tumor growth and enhanced the efficacy of anti-PD-1 treatment." (PMID 39119332, 2024). "CD36 is an important receptor that allows entry to not only lipid particles but also facilitates the entry of lipid-enriched vesicles from the tumor, prompting these cells to initiate their tumor-promoting activities." (PMID 39062552, 2024). "In the present study, we investigated whether the selective inhibition of CD36 could exert the direct antitumor effect and the immunomodulatory effects in OSCCs to elucidate the role of CD36-mediated lipid metabolism in OSCC tumor-bearing hosts." (PMID 39273384, 2024). "Furthermore, CD36 inhibition by pitavastatin or knockdown/knockout strategies significantly reduced cell viability and tumor progression." (PMID 38319449, 2024). "Thus, targeting CD36 emerges as a two-hit strategy targeting both tumour and immune cells in the treatment of metastasis." (PMID 38969865, 2024). "Regarding tumour mutational burden (TMB), CD36 was significantly positively correlated only in LUAD, while showing a significant negative correlation in THCA and STAD; MYD88 was significantly positively correlated with TMB in BLLCA, ESCA, STAD, but the opposite was found in CHOL, OV and UVM." (PMID 38742843, 2024).